PVT1 (Pvt1 oncogene)
Diseases named in the same sentence as PVT1 in open-access papers (continued):
Sharing a sentence is not in itself a finding about the gene and the disease.
pancreatic cancer (continued). "Functional inactivation of PVT1 resulted in the enhanced sensitivity to gemcitabine in pancreatic cancers." (PMID 34439315, 2021). "Study showed that functional inactivation of PVT1 resulted in enhanced gemcitabine sensitivity whereas overexpression of PVT1 enhanced resistance to gemcitabine in human pancreatic cancer." (PMID 34439315, 2021). "In pancreatic cancer, higher expression of PVT1 was found in cancer tissues, and the high expression of PVT1 was positively correlated with poor survival of patients." (PMID 34439315, 2021). "A previous genome-wide screen identified PVT1 as a regulator of gemcitabine sensitivity in pancreatic cancer cells." (PMID 34564701, 2021). "Collectively, these data suggest that the ability of HAT1 to induce PVT1 expression in pancreatic cancer cells requires BRD4." (PMID 34564701, 2021). "Our data strongly support that HAT1 upregulates PVT1 and promotes gemcitabine resistance in pancreatic cancer by enhancing BRD4 binding to the PVT1 promoter." (PMID 34564701, 2021). "We demonstrated that PVT1 specifically promotes pancreatic cancer cell resistance to gemcitabine via increased Wnt/β-catenin pathway signaling and autophagic activity." (PMID 32727463, 2020). "In the present study, we demonstrated that PVT1 was up-regulated in gemcitabine-resistant pancreatic cancer cell lines." (PMID 32727463, 2020). "Our findings provide insight into PVT1 to be a prognostic marker for pancreatic cancer chemosensitivity, as well as in the development of novel treatment against human pancreatic cancer." (PMID 32727463, 2020). "In this study, we attempted to investigate the contributions and mechanisms of the lncRNA PVT1 to the sensitivity of pancreatic cancer to gemcitabine." (PMID 32727463, 2020). "By fractionated nuclear and cytoplasmic RNA analysis in PANC-1 and ASPC-1 pancreatic cancer cells, we found that PVT1 was distributed in both the cytoplasm and nucleus." (PMID 32727463, 2020). "To investigate the biological role of the PVT1/miR-619-5p axis in human pancreatic cancer gemcitabine resistance, we assessed the viability of PANC-1 cells treated with gemcitabine at different concentrations for different durations." (PMID 32727463, 2020). "Taken together, these data indicate that PVT1 was up-regulated under gemcitabine treatment conditions and that a high level of PVT1 promoted pancreatic cancer cell resistance to gemcitabine in vitro and in vivo." (PMID 32727463, 2020). "Collectively, our findings highlight the role of PVT1 in the regulation of chemoresistance in pancreatic cancer." (PMID 32727463, 2020). "The lncRNAs HOTAIR and PVT1 had higher concentrations in saliva from pancreatic cancer patients than from healthy individuals, and their expression levels decreased after the patients underwent radical pancreatectomies." (PMID 32973402, 2020). "In summary, it is our novel discovery of a positive feedback loop between the lncRNA PVT1 and Wnt/β-catenin signaling involved in human pancreatic cancer gemcitabine resistance." (PMID 32727463, 2020). "The long noncoding RNA PVT1 was reported to be involved in carcinogenesis and chemoresistance; however, the mechanism by which PVT1 regulates the sensitivity of pancreatic cancer to gemcitabine remains poorly understood." (PMID 32727463, 2020). "One additional study indicated that lncRNA human plasmacytoma variant translocation 1 (PVT1) induces autophagy through increasing the protein and mRNA levels of Pygo2 and ATG14 and enhances cell resistance to gemcitabine in pancreatic cancer." (PMID 33239065, 2020). "An understanding of the level at which sponging by PVT1 take place was confirmed by measuring the effect of PVT1 on pre-miR-448 and pri-miR-448 in pancreatic cancer cells." (PMID 32117705, 2020). "Several lncRNAs such as Linc-ROR, AB209630, and PVT1 have been reported to be involved in gemcitabine resistance in pancreatic cancer." (PMID 30728036, 2019).
pancreatic cancer (continued). "The cancer risk-associated SNPs are differentially located on 8q24 in different cancers; for example, rs1561927 in pancreatic cancer locates 455 kb telomeric of PVT1, while rs10088218 in ovarian cancer lies 400 kb 3′ of MYC." (PMID 31309249, 2019). "In pancreatic cancer, PVT1 has been found to promote EMT by downregulation of the cyclin-dependent kinase p21." (PMID 29701689, 2018). "PVT1 induces EMT and migration in oesophageal and pancreatic cancer cells with increased expression associated with advanced disease stage and metastasis." (PMID 28430163, 2017). "In conclusion, our study suggested that PVT1, HOTTIP, MALAT1 was associated with the efficacy of first-line treatment with GEM based chemotherapy in pancreatic cancer." (PMID 29221115, 2017). "The results suggest that MALAT1, HOTTIP and PVT1 as predictors to predict the efficacy of GEM based chemotherapy in first-line treatment of pancreatic cancer patients." (PMID 29221115, 2017). "In pancreatic cancer cells, knockdown of PVT1 inhibited cell proliferation, migration and epithelial-mesenchymal transition (EMT) by regulating p21 expression." (PMID 29108264, 2017). "In previous studies, HOTAIR and PVT1 were demonstrated to be novel biomarkers for the early diagnosis of pancreatic cancer." (PMID 29207609, 2017). "Compared with normal pancreatic tissues (NPT), the expression of HOTAIR, HOTTIP, and PVT1 exhibited significant elevation in pancreatic cancer tissues (PCT) (p values were 0.025, 0.006, and 0.016, respectively)." (PMID 27028998, 2016). "Functional inactivation of the PVT1 contributes to enhanced Gemcitabine sensitivity in human pancreatic cancer ASPC-1 cells, vice versa." (PMID 27028998, 2016). "Compared with benign pancreatic tumour (BPT) and normal pancreatic tissues (NPT), HOTAIR, HOTTIP and PVT1 were significantly up-regulated in pancreatic cancer tissues (PCT)." (PMID 27028998, 2016). "Overexpression of PVT1 in the pancreatic cancer cell line ASPC-1 resulted in decreased gemcitabine sensitivity." (PMID 25910082, 2015). "PVT1 overexpression has been demonstrated in pancreatic cancer and colon cancer, and is related to poor prognosis in most of these cases." (PMID 26703666, 2015). "PVT1 can stimulate the Wnt/β-catenin signaling pathways and autophagy through the function of miR-619-5p in the miR-619-5p/autophagy-related 14 (ATG14) and miR-619-5p/pygopus homolog 2 (Pygo2) axes, causing chemo-resistance promotion in pancreatic cancer." (PMID 38559560, 2024). "In addition to H19, PVT1 has been shown to increase EMT in pancreatic cancer tissue by activating the TGF-β/SMAD signaling pathway and inducing proliferation and metastasis by inhibiting SERPINE1 mRNA binding protein 1 (SERBP1)." (PMID 38559560, 2024). "Thus, evaluating the status of PVT1-MYC duet is a powerful method for prognosis estimation of pancreatic cancer." (PMID 39376555, 2024). "Pvt1 oncogene (PVT1) is upregulated in gemcitabine-resistant pancreatic cancer cell lines, and PVT1 promotes Pygopus family PHD finger 2 (Pygo2) and ATG14 expression; the PVT1/miR-619-5p/Wnt/β-catenin axis promotes cellular autophagy and attenuates resistance to gemcitabine." (PMID 38481525, 2024). "Nonetheless, the prognostic values and critical regulatory networks of PVT1-MYC duet in pancreatic cancer remain unclear." (PMID 39376555, 2024). "Finally, we detected PVT1 expression in pancreatic cancer and paracancer tissues from the PUMCH cohort, which showed that PVT1 was significantly upregulated in pancreatic cancer and associated with invasion, metastasis, and poor prognosis." (PMID 39376555, 2024). "The results of this study may help to improve the current plight of the mechanism of PVT1-MYC duet in pancreatic cancer and the therapeutic strategies targeting PVT1-MYC duet-related processes." (PMID 39376555, 2024).
pancreatic cancer (continued). "More studies are needed to reveal new perspectives about PVT1-MYC duet in pancreatic cancer progression, which may provide a new insight on pancreatic cancer therapy." (PMID 39376555, 2024). "We finally detected PVT1 expression in pancreatic cancer tissues and tumor-adjacent normal tissues by ISH method and analyzed the correlation between PVT1 expression and clinicopathological parameters, and confirmed the function of PVT1 and signature genes in the progression of PDAC." (PMID 39376555, 2024). "However, the roles of PVT1-MYC duet-related genes for pancreatic cancer immune microenvironment are still unclear." (PMID 39376555, 2024). "Moreover, since CDC6 consistently yielded positive results in previous proliferation and migration assays, it suggests that CDC6 is a key downstream factor in the promotion of pancreatic cancer progression by the PVT1-MYC duet." (PMID 39376555, 2024). "PVT1 also regulates the development and progression of pancreatic cancer." (PMID 38559560, 2024). "Tumor-associated nonmyelinating Schwann cell-expressed PVT1 promotes pancreatic cancer kynurenine pathway and tumor immune exclusion." (PMID 39050547, 2024). "Then, we were wonder about the roles of PVT1-MYC duet in pancreatic cancer progression." (PMID 39376555, 2024). "Besides, studies have shown that PVT1 regulates gemcitabine sensitivity in pancreatic cancer via miR1207 and thus plays a role in drug resistance." (PMID 38559560, 2024). "Given the role of the PVT1/HIF-1α regulatory loop in the progression of pancreatic cancer, this path may be one of the promising therapeutic goals in managing pancreatic cancer." (PMID 38559560, 2024). "In addition, lncRNA PVT1 was observed to promote autophagy and gemcitabine resistance in pancreatic cancer by regulating miR-619-5p/ATG14 via the Wnt/β-catenin pathway." (PMID 36899946, 2023). "In addition, oncogenic lncRNA PVT1 was found to be an independent prognostic factor for poor overall survival in patients with pancreatic cancer." (PMID 34439315, 2021). "In addition, several ncRNAs such as AFAP1-AS1, UCA1, HOTAIR, PVT1, MALAT-1, circ-ADAM9, BC008363, circ-LDLRAD3, circ-IARS, circ-PDE8A, circ_0030235, and circ_0001649 have been associated with prognosis of pancreatic cancer." (PMID 34439315, 2021). "Furthermore, analysis using GEPIA indicated a strong positive correlation between BRD4 and PVT1 levels in pancreatic cancer specimens." (PMID 34564701, 2021). "In addition, PVT1 also promoted pancreatic cancer development through regulation of miR519, HIF-1, YKT6, RAB7, and VAMP3, suggesting its diverse oncogenic effects with multiple signaling regulation." (PMID 34439315, 2021). "PVT1 is a lncRNA and significantly overexpressed in pancreatic cancer." (PMID 34439315, 2021). "Notably, a previous genome-wide screening identified PVT1 as a critical regulator of gemcitabine sensitivity in pancreatic cancer." (PMID 34564701, 2021). "Our findings suggest that HAT1-induced gemcitabine resistance in pancreatic cancer may be mediated by the PVT1/EZH2 complex." (PMID 34564701, 2021). "Furthermore, analyses using the GEPIA tool and ENCORI Pan-Cancer Analysis Platform indicated a positive correlation between HAT1 and PVT1 expression levels, suggesting that HAT1 regulates PVT1 expression in pancreatic cancer cells." (PMID 34564701, 2021). "Furthermore, PVT1 also took part in drug resistance of pancreatic cancer by interacting with ATG14 and promoting PtdIns3K activity." (PMID 33868366, 2021). "Additionally, silencing of the long noncoding RNA (lncRNA) PVT1 increased gemcitabine sensitivity in pancreatic cancer cells." (PMID 34564701, 2021). "However, the functional roles and mechanisms of PVT1 in the sensitivity of pancreatic cancer to gemcitabine treatment remain poorly understood and thus need to be further clarified." (PMID 32727463, 2020). "LncRNA PVT1 promoted gemcitabine resistance of pancreatic cancer via sponging miR-619-5p." (PMID 33401249, 2020).
pancreatic cancer (continued). "We further investigated whether PVT1 affects the apoptosis rate of pancreatic cancer cells induced by gemcitabine." (PMID 32727463, 2020). "For rs1561927, it was identified as a risk locus for pancreatic cancer, which located at 455kb telomeric of PVT1, a nongenic region between PVT1 and LINC0097726." (PMID 31897242, 2020). "The long noncoding RNA plasmacytoma variant translocation 1 (PVT1) is upregulated in pancreatic duct adenocarcinoma (PDAC) tissues and has been shown to promote pancreatic cancer cell proliferation and migration, and epithelial-to-mesenchymal transition (EMT), by downregulating p21cip1/waf1." (PMID 31514410, 2019). "Besides, PVT1 was also identified as a regulator of Gemcitabine sensitivity and functional inactivation of it led to enhanced Gemcitabine sensitivity in human pancreatic cancer cells." (PMID 27628540, 2016). "In this regard, we found an approximately 6-fold upregulation of lncRNA PVT1 in pancreatic cancer." (PMID 25910082, 2015). "LncRNA plasmacytoma variant translocation 1 gene (PVT1), located at 8q24.21, was significantly upregulated and therefore identified as an oncogene in the progression of diverse human cancers, such as non-small cell lung cancer (NSCLC), pancreatic cancer, esophageal cancer, and CC." (PMID 33817293, 2021). "Additionally, functional inactivation of the PVT1 gene could enhance gemcitabine sensitivity, whereas ectopic expression of PVT1 reversed this effect in ASPC-1 human pancreatic cancer cells." (PMID 32727463, 2020). "PCA showed that the distribution of PVT1-MYC duet-related genes differs between normal pancreatic tissues and pancreatic cancer samples." (PMID 39376555, 2024). "This study constructed a prognostic model based on three PVT1-MYC duet-related genes, which had a significant potential in predicting the prognosis and tumor microenvironment of pancreatic cancer." (PMID 39376555, 2024). "Suppression of miR-519d-3p by PVT1 increases the HIF-1α expression, triggers the Wnt/β-catenin signaling pathway, and promotes the growth and proliferation of pancreatic cancer cells." (PMID 38559560, 2024). "Furthermore, previous reports have confirmed that PVT1 is widely involved in the proliferation, invasion, metastasis, and multidrug resistance of digestive tract tumor cells, such as esophageal adenocarcinoma, colorectal cancer, gallbladder cancer, and pancreatic cancer." (PMID 37263709, 2023). "Curcumin improved GEM sensitivity in pancreatic tumor cells via EZH2 blocking and its downstream target PVT1." (PMID 37580768, 2023). "The chemoresistance ability was also regulated by PVT1 regulating autophagy signaling pathway, Wnt signaling pathway, and PI3K/AKT signaling pathway in cervical, osteosarcoma, or pancreatic cancer." (PMID 35256612, 2022). "Zhao and his partners declared that PVT1 was a sponge of miR-448 to upregulate SERBP1, thereby facilitating proliferation and migration of pancreatic cancer cells." (PMID 33817293, 2021). "The long noncoding RNA PVT1 (lncRNA PVT1) has been shown to interact with enhancer of zeste 2 polycomb repressive complex 2 subunit (EZH2), promoting gemcitabine resistance in pancreatic cancer." (PMID 34564701, 2021). "In this study, we found histone acetyltransferase 1 (HAT1) enhanced the tolerance of pancreatic cancer cells to gemcitabine and HAT1-mediated resistance mechanisms were regulated by PVT1 and EZH2." (PMID 34564701, 2021). "PVT1 also promoted autophagy and cell growth by regulating miR-20a-5p and ULK1 signaling, leading to the development of pancreatic cancer." (PMID 34439315, 2021). "We also indicated that PVT1 modulates gemcitabine resistance by the miR-619-5p/Pygo2 and miR-619-5p/ATG14 axes in pancreatic cancer cells." (PMID 32727463, 2020). "Taken together, our data demonstrated that PVT1 functions as a ceRNA to regulate the miR-619-5p/Pygo2 and miR-619-5p/ATG14 axes to improve pancreatic cancer chemoresistance." (PMID 32727463, 2020).
pancreatic cancer (continued). "A study done on gemcitabine resistance in pancreatic cancer noted that curcumin down-regulates the expression of EZH2, PVT1 and their down-stream targets in gemcitabine-resistant cells." (PMID 32117705, 2020). "However, few studies focused on the prognostic value of PVT1-MYC duet related genes and the potential targets of the duet in pancreatic cancer." (PMID 39376555, 2024). "Therefore, we subsequently focused on exploring the functions and mechanisms of PVT1, CDC6 and COL17A1 in pancreatic cancer." (PMID 39376555, 2024). "One study found that PVT1/miR-619-5p/Pygo2 and PVT1/miR-619-5p/ATG14 regulatory axes could mediate gemcitabine resistance in pancreatic cancer cells by activating Wnt/β-catenin signaling pathway and autophagy signaling pathway respectively." (PMID 38811958, 2024). "Also, increasing the amount of PVT1 with MALAT1 and HOTTIP in serum has been suggested to predict the effect of gemcitabine in pancreatic cancer." (PMID 38559560, 2024). "It was also found that the interaction of PVT1 and ATG14 facilitates the formation of the autophagy-specific complex I (PtdIns3K-C1) and class III PtdIns3K activity, thereby initiating autophagy in pancreatic cancer." (PMID 36899946, 2023). "Moreover, upregulated PVT1 can activate Wnt/β-catenin signaling pathway by regulating expression of both Pygo2 and ATG14 and thus promote autophagy related complex in pancreatic cancer." (PMID 35392800, 2022). "LncRNA PVT1 was significantly upregulated in pancreatic cancer cell lines and tissues and could promote EMT in pancreatic cancer cells by downregulating p21, which directly regulates the expression of Snail." (PMID 35819532, 2022). "In addition, PVT1 has been found to be overexpressed in multiple other cancers including CRC, non-small cell lung cancer (NSCLC) and pancreatic cancer." (PMID 33652661, 2021). "Interestingly, PVT1 has been found to form a complex with EZH2, a key step in the development of gemcitabine resistance in pancreatic cancer." (PMID 34564701, 2021). "Herein, we show that HAT1 knockdown in pancreatic cancer cells increases gemcitabine sensitivity and decreases PVT1/EZH2 complex levels, suggesting that HAT1 may represent a promising therapeutic target in pancreatic cancer." (PMID 34564701, 2021). "PVT1 had also been shown to bind EZH2, it was consistent in pancreatic cancer cells." (PMID 34564701, 2021). "We also found that PVT1/miR-619-5p could target ATG14 and promote cellular autophagic activity, and pharmacological or genetic inhibition of autophagy activity restored pancreatic cancer gemcitabine sensitivity." (PMID 32727463, 2020). "PVT1 can promote EMT and migration by down regulating p21 in pancreatic cancer cells." (PMID 30679629, 2019). "Pvt1 oncogene (PVT1) is an lncRNA that is greater than 30 kb in size and is upregulated in cancers (especially various cancers of the digestive system, including esophageal, gastric, primary liver, and pancreatic cancer and CRC) and can promote tumor cell proliferation, migration, and invasion." (PMID 33996548, 2021). "Therefore, HOTAIR and PVT1 detection in saliva may be used as a sensitive and noninvasive method to differentiate pancreatic cancer patients from healthy individuals or those with benign pancreatic lesions." (PMID 32973402, 2020). "Patients with high PVT1 expression exhibited poor overall survival, PVT1 could be an independent prognostic factor for patients with PDAC.Salivary PVT1 were also up-regulated in the saliva of patients, might serve as potential non-invasive biomarker for diagnosis of pancreatic cancer." (PMID 29108264, 2017).